CCL5 (C-C motif chemokine ligand 5)
Diseases named in the same sentence as CCL5 in open-access papers (continued):
Sharing a sentence is not in itself a finding about the gene and the disease.
melanoma (194 papers, 1999 to 2026). A malignant, usually aggressive tumor composed of atypical, neoplastic melanocytes. "We next tested the impact of FIH on the directional migration of macrophages toward chemokine CCL5, which is known to be associated with an altered myeloid or T cell involvement in melanoma (42, –44)." (PMID 38422022, 2024). "Both DTIC and TMZ have been found to cause melanoma cells to secrete chemokines like CCL5, CXCL9, CXCL10, and CXCL11 in an animal model of melanoma." (PMID 38057843, 2023). "CCL5 overexpression was associated with significantly improved long-term survival in patients with melanoma." (PMID 36936940, 2023). "Autophagy inhibition in melanoma cells also renders improved tumor killing by NK cells via upregulating chemokine CCL5 expression, as autophagy deficiency leads to PP2A deactivation and thus promotes JNK-c-Jun-CCL5 axis activity." (PMID 37425656, 2022). "Becn1/Beclin1-deficient melanoma cells in the TME expressed high levels of CCL5 via the activation of the MAPK8/JNK-JUN/c-Jun signaling pathway, which boosted the infiltration of functional NK cells into the TME and curtailed tumor progression." (PMID 36300110, 2022). "High expression of CCL4 and CCL5 are associated with better outcome in melanoma, endometrial, and colorectal cancer, but with worst outcome in renal cancer." (PMID 30873179, 2019). "Clinically, a high level of CCL5 is positively associated with the NK cell marker NKp46 as well as with melanoma patients’ survival." (PMID 31252639, 2019). "The conclusion is that the CCL5/CCR5 axis seems associated with melanoma progression due to increased levels of immunosuppressive cells." (PMID 24523569, 2014). "CCL5 is higher in melanoma cells than in normal melanocytes and is associated with a higher malignancy state and increased tumor formation." (PMID 24523569, 2014). "Moreover, loss of CCL5 expression was found to be associated with enhanced melanoma aggressiveness and poor therapeutic response." (PMID 30873179, 2019). "Furthermore, when autophagy was inhibited in melanoma cells by either ATG5 or p62/SQSTM1 deficiency or CQ treatment, melanoma cells could recruit NK cells into the tumor site by CCL5 releasing." (PMID 36300110, 2022). "In conclusion, IκBζ expression in melanoma inhibits tumor infiltration of cytotoxic T cells, probably by suppressing the expression of chemokines, such as Ccl5, Cxcl9, and Cxcl10." (PMID 40562773, 2025). "In particular, both CCL5/Rantes and CXCL10/IP10 mRNA, and their corresponding secreted proteins, were significantly up-regulated in autophagy-deficient melanoma cells." (PMID 40611330, 2025). "Together this data confirms that constitutive IκBζ expression in melanoma contributes to immunotherapy resistance, supposably by suppressing Ccl5, Cxcl9, and Cxcl10 expression, leading to a continuous exclusion of cytotoxic T cells and NK cells from the TME." (PMID 40562773, 2025). "We previously demonstrated that B16-F10 melanoma cells, which are resistant to anti-PD-1 therapy in vivo, exhibit relatively low expression of CCL5 and CXCL10, two key chemokines essential for recruiting NK and CD8+ T cells to the tumor microenvironment." (PMID 40248897, 2025). "CCL5 high expression level is correlated with better overall survival in patients with melanoma (PRJEB23709 and TCGA_SKCM)." (PMID 40995650, 2025). "The expression of CCL5 is higher in pre‐therapy tissues from responders than that from non‐responders in two melanoma datasets (GSE91061 and PRJEB23709)." (PMID 40995650, 2025). "CCL5 expression was higher in T cell-inflamed melanoma metastases, suggesting its important role in CD8+ T cell recruitment into the tumor microenvironment." (PMID 38928238, 2024). "External datasets pertaining to melanoma or HCC suggested that immunotherapy is responsible for the upregulation of CCL5 expression." (PMID 39183447, 2024). "In contrast, IL32 induces ICI-resistant melanoma by activating DCs to secrete CCL5-primed CD8+ TILs." (PMID 38343549, 2024).
melanoma (continued). "In melanoma and CRC tumor models, the effects are NK and CD8+ T cell‐dependent and associated with increased levels of chemokines CCL5 and CXCL10." (PMID 38506049, 2024). "Our data revealed heightened expression of CD8+ T cell markers (CD8a and CD8b) and NK cell markers (NCR1 and NCR3) in melanoma patients with elevated levels of cGAS/CCL5/CXCL10." (PMID 38506049, 2024). "Expanding upon these clinical observations, we have demonstrated that melanoma patients with elevated cGAS levels also exhibit increased expression of CCL5 and CXCL10, as illustrated in." (PMID 38506049, 2024). "We observed positive correlations between three types of NLS and T-cell receptor-associated gene expression signatures, such as CD8A, CD3G, CCL5, TIGT, LCK and IKZF3 in lung cancers and primary melanomas after adjusting clinical factors." (PMID 37100920, 2023). "These anti-tumor immune cell infiltrations by Vps34 inhibition are caused by the upregulation of certain chemokines, CCL5 and CXCL10, thereby improving ICI therapeutic efficacy in melanoma and colorectal cancer mouse models." (PMID 38067169, 2023). "The ligand, CCL5 is expressed in T lymphocytes, macrophages, platelets, synovial fibroblasts, tubular epithelium and various cancers, such as melanoma." (PMID 37170733, 2023). "Targeting autophagy in a CCL5-dependent manner improves NK cell infiltration and inhibits melanoma growth." (PMID 36936940, 2023). "Since the chemokine CCL5 is known to recruit CD8+ T lymphocytes to the site of inflammation, the frequency of CD8+ T infiltration in tumors was correlated with the CCL5 expression in a cohort of 480 melanoma samples of the TCGA dataset." (PMID 37730606, 2023). "For example, CCL5 (Chemokine (C-C motif) ligand 5) secreted by Aurora kinase A (AURKA) or CDK4/6 inhibitor-induced melanoma senescent cells promotes the recruitment of tumor-infiltrating leukocytes (TILs), enhancing their killing effect on tumor cells." (PMID 37174106, 2023). "Based on these data, the effect of PRELP overexpression on CCL5 secretion in Buf1088 melanoma cells was determined using the ELISA." (PMID 37730606, 2023). "By applying this approach, we observed that CCL5 significantly and positively correlated with monocyte infiltration in melanomas." (PMID 36418472, 2023). "Significantly higher levels of Ifng, Nos2, Il12, Ccl5, Cx3cl1, and Cxcl9 — and, by contrast, significantly lower levels of Arg1 — were detected in the melanomas of Colec11–/– mice, compared with WT mice." (PMID 36883567, 2023). "Strikingly, inhibition of NF-κB in Bcl-xL overexpressing melanoma cells also reduced the number of recruited macrophages, phenocopying the effects of CCL5 inhibition." (PMID 37488586, 2023). "Silencing of CCL5 in Beclin 1 KO melanoma cells reverts the ability of autophagy inhibition to regulate tumor regression and NK infiltration." (PMID 38071322, 2023). "CCL5 levels are high in patients with hot melanoma vs. cold melanoma and CCL5-high tumors express more effector immune cells (Th1, NK, CD8+ T cells)." (PMID 37759462, 2023). "This is further in line with a reduced expression of CCL5 in PRELPlow melanoma, which is a potent chemoattractant for T cells." (PMID 37730606, 2023). "As up-regulated genes (IL-8, IL-1β, MCSF and CCL5) in Bcl-xL overexpressing melanoma cells have in common that are all regulated by NF-κB, we evaluated if this transcription factor was the intermediary between Bcl-xL and the release of these cytokines." (PMID 37488586, 2023). "In contrast, inhibition of CCL5 production by melanoma cells only affected the recruitment of macrophages, suggesting that these tumor-derived factors can impact the function of resident macrophages in distant sites to sustain tumor aggressiveness." (PMID 37488586, 2023). "We previously reported that driving NK cells to melanoma tumors depends on the release of CCL5 to the tumor microenvironment by tumor cells." (PMID 35795658, 2022).
melanoma (continued). "The expansion and migration of MDSCs, which are the precursors of macrophages, granulocytes, and DCs, are influenced by C-C chemokine receptor type 5 (CCR5) ligands (CCL3, CCL4, and CCL5) in melanoma." (PMID 35334544, 2022). "In melanoma cells, Beclin-1 inhibition prevented Granzyme B degradation and increased NK cell infiltration in a CCL5-dependent manner, thereby inhibiting melanoma growth." (PMID 36009363, 2022). "A similar improvement in tumor infiltration by natural or adoptively transferred NK cells has been documented in preclinical melanoma models secreting CCL5 downstream of viral infection, as well as in models of HCC receiving a CCL5-coding adenoviral vector." (PMID 36319998, 2022). "We further showed that melanoma patients having low Winter hypoxia score survive better and show increased CCL5 as well as high tumor infiltration by NK and CD8 T-cells versus those having a high hypoxia score." (PMID 35795658, 2022). "Melanoma involves upregulation of pro-inflammatory cytokines, such as IL-6, IL-8, C-C chemokine ligand 5 (CCL5), and IL-1β, along with VEGF." (PMID 35334544, 2022). "For other chemokines, most of them tended to express higher in FGFR Mut melanoma, such as CCL5, CCL19, CXCL9, CXCL10, CXCL11, CXCL13 and CXCL14 (all P > 0.05)." (PMID 36426352, 2022). "In humans, the chemokines CCL2, CCL3, CCL4, CCL5, CXCL9, and CXCL10 have been associated with increased T cell infiltrates in melanomas, and the same chemokines were confirmed to attract human CD8+ T cells in vitro." (PMID 34454518, 2021). "As an example, arenavirus-infected melanoma cells produce a high level of CCL5, leading to recruitment of NK cells and melanoma regression." (PMID 33546172, 2021). "Although these findings were observed in mouse models, the same study found a positive correlation between survival and high expression of CCL5 in melanoma patients, confirming that this chemokine plays an important role in the human setting." (PMID 34572949, 2021). "SFN and combinatorial treatment with 5-aza-2′-deoxycytidine (DAC) showed the significant inhibition of melanoma cell growth with a marked increase in CCL5, DUSP15, and IL33 expression." (PMID 34835969, 2021). "CCL5 is a cytokine known as a chemoattractant for natural killer (NK) cells involved in inhibiting melanoma growth." (PMID 34835969, 2021). "The literature indicates that, like Beclin-1, other autophagy-related proteins, including Atg5, p62/SQSTM1 and chloroquine, which pharmacologically inhibits autophagy, also induce the expression of selected chemokines, e.g., CCL5 in melanoma cells." (PMID 34204085, 2021). "In melanoma patients, we revealed that tumors exhibiting high CCL5 are less hypoxic, and displayed high NK, CD3+, CD4+ and CD8+ T cell markers than those having low CCL5." (PMID 34155342, 2021). "In melanoma, NK cells are recruited by the inflammatory chemokines CCL5 and CXCL9-11, expressed within the TME, by the engagement of the cognate receptors CCR5 and CXCR3, respectively." (PMID 34712615, 2021). "In a preclinical model of melanoma, it has been shown that a gradient of CCL5 was needed for the recruitment of NK cells either to the primary tumor or to metastasis." (PMID 34203391, 2021). "Beclin-1 targeting for inhibiting autophagy in melanoma cells has been shown to result in recruitment of natural killer (NK) cells in the tumor bed via C-C motif chemokine ligand 5 (CCL5) induction, thereby leading to tumor growth suppression." (PMID 33809137, 2021). "In line with the CCL5 expression, Ma-Mel-51 melanomas grew similarly in NSG mice compared to NOD/SCID mice, suggesting that NK cells do not affect Ma-Mel-51 growth." (PMID 32973762, 2020). "It has also been demonstrated, however, that targeting Beclin-1 in melanoma cells increased the infiltration of natural killer (NK) cells into melanoma tumors that was dependent on increased expression of the C-C motif chemokine ligand 5 (CCL5)." (PMID 32340261, 2020).
melanoma (continued). "We concluded that the strong anti-tumoral effects of LCMV in Ma-Mel-86a melanoma cells correlated with enhanced CCL5 production in vivo." (PMID 32973762, 2020). "In the present study we identified CCL5 production as one important factor determining the efficacy of treatment of melanoma with LCMV." (PMID 32973762, 2020). "In our current investigation, we used the non-cytopathic LCMV in different human melanoma models and found that melanoma cell lines produced high levels of CCL5 in response to immunotherapy." (PMID 32973762, 2020). "Deletion of the proximal enhancer decreases CCL5 expression and augments the cytotoxic activity of tissue-resident T and NK cells, which coincides with reduced melanoma metastasis in mouse models." (PMID 32218434, 2020). "We demonstrate that induction of CCL5 by LCMV is specific for a subgroup of melanomas and that transgenic expression of CCL5 in a melanoma cell line enhances the responsiveness of LCMV therapy." (PMID 32973762, 2020). "A strong positive correlation between the expression of CCL5 and the infiltration of NK cells into human melanoma biopsies as well as various other solid tumors was previously demonstrated." (PMID 32973762, 2020). "In conclusion, we identified CCL5 and NK cell-mediated cytotoxicity as new factors influencing melanoma regression during virotherapy." (PMID 32973762, 2020). "Using an in vivo model of human melanoma, we found that LCMV treatment resulted in strong CCL5 production, NK cell infiltration and CCL5-dependent immune-mediated melanoma regression." (PMID 32973762, 2020). "Taken together, we conclude that NK cells are recruited into the tumor tissue after LCMV mediated tumoral expression of CCL5 and that the NK cells exert strong anti-tumoral effects in the Ma-Mel-86a melanoma cells." (PMID 32973762, 2020). "To molecularly corroborate the phenotype, we made use of the B16-Ova murine melanoma cell line overexpressing CCL5 (B16-Ova-CCL5) and compared them to control cells (B16-Ova-Empty) following LCMV therapy." (PMID 32973762, 2020). "CCL5 is secreted by certain types of tumor cells, and clinical studies show that elevated levels of CCL5 in tissues and plasma reflect adverse conditions for patients with melanoma, breast, cervical, prostate, gastric, or pancreatic cancer." (PMID 32260550, 2020). "CCL5 expression in a murine model of spontaneous melanoma correlated with CD3γ expression and T cell recruitment, while increased level of CCR5, the receptor for CCL5, was associated with positive outcomes in melanoma models due to T cell retention in tumors." (PMID 30899263, 2019). "Clinical data indicate that CCR5 ligands, CCL4, and CCL5, can promote anti-melanoma immune response." (PMID 30873179, 2019). "CCL5 is the main factor in inhibiting melanoma growth by bringing NK cells to the tumor site, while autophagy is suppressed." (PMID 31252639, 2019). "Contrary to that, targeting Beclin-1 inhibits autophagy, overexpresses CCL5 and aids in recruit NK cells to the melanoma tumor." (PMID 29988591, 2018). "For example, in melanoma, the upregulation of chemokine genes, such as Ccl2, Ccl3, Ccl4, Ccl5, Cxcl9, and Cxcl10, in the tumor microenvironment correlates with the influx of activated T cells into the tumor supporting the antitumor immune response." (PMID 29410666, 2018). "In melanoma, elevated tumor levels of T lymphocytes are associated with a better prognosis and elevated expression of CXCL9 and CCL5 has been associated with a better response in metastatic melanoma patients." (PMID 29137331, 2017). "Previously, we found that melanoma-activated TIL induced MSCs to produce a wide variety of chemokines including the Th1 chemokines CCL5, CXCL9, CXCL10 and CXCL11 and the Th1 cytokine IL-125." (PMID 27211104, 2016). "The expression of chemokines such as CCL5, CXCL10 and others were associated with malignant melanoma progression." (PMID 26197340, 2015).
melanoma (continued). "It has been reported that CCL5 is secreted by melanoma cells in vivo and in vitro, and is able to recruit diverse tumor-infiltrating leucocytes (TIL)." (PMID 25658320, 2015). "We briefly summarize the role of CCL5/CCR5 in melanoma and gastric, ovarian, cervical, colorectal, and prostate cancer." (PMID 24523569, 2014). "CCL-5-expressing melanoma cells generate tumors in mice, and the tumor burden is correlated with CCL-5 levels." (PMID 23342280, 2012). "For example, CXCL1-3, CXCL-8, and CCL-5 have been reported to favor melanoma growth and/or progression." (PMID 23342280, 2012). "We have previously shown that reovirus infection of human melanoma cell lines induces a potentially immunogenic form of cell death with the release of RANTES (CCL5), IL-8, MIP-1α (CCL3) and MIP-1β (CCL4)." (PMID 21338484, 2011). "Increased CCL5 levels are markers of an unfavourable outcome in patients with melanoma, breast, cervical, prostate, gastric or pancreatic cancer." (PMID 22205974, 2011). "Quantitative analysis unravelled increased CCL5 production from AT-MSC in response to melanoma cells." (PMID 20509882, 2010). "In a melanoma mouse model, we demonstrated that Ackr2 inhibition increases the release of proinflammatory chemokines CCL5 and CXCL10 and enhances the infiltration of NK cells, activated CD8+ and CD4+ effector T cells while reducing regulatory T cells (Tregs) in the TME." (PMID 40248897, 2025). "Moreover, the post‐treatment tumor tissues of responders exhibited higher CCL5 expression than those of non‐responders in patients with melanoma (GSE91061), gastric cancer (PRJEB25780), and non‐small cell lung cancer (GSE135222)." (PMID 40995650, 2025). "CCL5 expression was also found to be upregulated by anti‐PD1 therapy in melanoma." (PMID 39183447, 2024). "Furthermore, the induction of IRF reporter and CCL5 secretion by OSU13 was abrogated in mouse melanoma and human colon cancer cells with Sting gene KO." (PMID 38900577, 2024). "Vice versa, reduced PRELP expression in melanoma cells is associated with low expression levels of MHC class I APM components and members of the IFN-γ signal transduction as well as CCL5, which could be reconstituted by PRELP overexpression." (PMID 37730606, 2023). "The high expression of CCL5 is also shown in melanoma patients with higher survival rates." (PMID 38067169, 2023). "In addition, a high frequency of intra-tumoral T cells directly correlated with the expression of MHC class I and PRELP as well as the T cell attractant CCL5 in melanoma lesions." (PMID 37730606, 2023). "Some melanomas induce the secretion of C-C motif chemokine ligand 5 (CCL5), a chemokine that participates in the apoptosis of harmful maternal CD3+ cells in tumor-infiltrating lymphocytes, which causes the cells to undergo apoptosis as a method to avoid immune rejection." (PMID 36834865, 2023). "Indeed, a positive correlation exists between increased numbers of tumor-infiltrating monocytes and CD8+ T cells and the expression of CCL5 in melanoma, but also in other types of cancer, which further helped the recruitment of CD8+ effector T cells." (PMID 37730606, 2023). "Our findings suggest that PRELP induces the expression of MHC class I and CCL5 in melanoma, which might be involved in an enhanced T cell recruitment and immunogenicity associated with an improved patients’ outcome." (PMID 37730606, 2023). "In addition, melanoma patients with high CCL5 in their tumors survive better than those having low CCL5." (PMID 34155342, 2021). "Moreover, autophagy inhibition in melanoma cells has been demonstrated to enhance NK cell infiltration via CCL5 production through c-Jun activation." (PMID 33809137, 2021). "Notably, higher expression of CCL5 is correlated with increased level of NKp46 and longer survival in melanoma patients." (PMID 35008589, 2021).